EBLN3P (endogenous Bornavirus like nucleoprotein 3, pseudogene)
Diseases named in the same sentence as EBLN3P in open-access papers (continued):
Sharing a sentence is not in itself a finding about the gene and the disease.
tumor (continued). "Expression analyses from the other two independent datasets (GSE29079, GSE94767) showed four (AC004542.2, ZFAS1, EBLN3P, GAS5) out of nine lncRNAs were significantly overexpressed in tumor." (PMID 36514044, 2022). "The results showed that AC005261.1, LINC01578, ZFAS1, EBLN3P, THUMPD3-AS1 and GAS5 were highly expressed in tumor than adjacent normal samples." (PMID 36514044, 2022). "Taken together, the lncRNAs in common (EBLN3P, AC004542.2, ZFAS1, and GAS5) seemed the most potentially predictive or prognostic genes for PCa that were closely related to the tumor progression." (PMID 36514044, 2022). "In this study, we also performed in vitro experiments, finding that knockdown of EBLN3P suppressed the proliferation, migration, and invasion of SW480 and HCT116 and promoted apoptosis, suggesting EBLN3P as a tumor promoter in CRC progression." (PMID 34109193, 2021). "We aimed to determine lncRNA endogenous bornavirus-like nucleoprotein (EBLN3P) expression in CRC and examine its influence on tumor behaviors of CRC cells." (PMID 34109193, 2021). "Moreover, the TCGA data also showed again that ZFAS1, EBLN3P, or GAS5 was overexpressed in PCa tumor compared to adjacent normal samples." (PMID 36514044, 2022). "EBLN3P and ANXA3 might have potential roles in the diagnosis, treatment, and prognosis of OS, and this study provided a theoretical reference for further clinical research in tumor surgery." (PMID 37598115, 2023).
cancer (7 papers, 2021 to 2023). A tumor composed of atypical neoplastic, often pleomorphic cells that invade other tissues. "One lncRNA module was confirmed to be associated with cancer metastasis, and nine hub lncRNAs, namely FTX, AC005261.1, NORAD, LINC01578, AC004542.2, ZFAS1, EBLN3P, THUMPD3-AS1, and GAS5, were discovered." (PMID 36514044, 2022). "LncRNA bornavirus-like nucleoprotein (lncRNA EBLN3P) has been reported to be abnormally expressed in various cancers." (PMID 35220878, 2022). "Among these lncRNAs only LINC00957, AL035661.1, and EBLN3P had already been studied in cancer context." (PMID 34136413, 2021). "In the present study, we hypothesized that lncRNA EBLN3P plays a cancer-promoting role in T-ALL through regulating miR-655-3p expression." (PMID 35220878, 2022). "LncRNAs EBLN3P and miR-655-3p participate in the development of various cancers." (PMID 35220878, 2022). "Despite showing a regulatory function in different cancer types, here we demonstrated a coding capacity of EBLN3P in hASC, which represents a possible dual-function of this transcript in stem cell biology, including a putative secreted smORF-derived microprotein." (PMID 34827671, 2021). "For the in-depth exploration of the basic molecular systems allowing EBLN3P to regulate downstream effectors inside CRC, this study first reported its site in carcinoma cells, given that lncRNA functions are dependent on its subcellular localization." (PMID 34109193, 2021).
EBLN3P also shares sentences with these, for which no sentence is quoted: colorectal cancer (6 papers); bladder cancer (1).